IL1B (interleukin 1 beta)
Diseases named in the same sentence as IL1B in open-access papers (continued):
Sharing a sentence is not in itself a finding about the gene and the disease.
infection (continued). "Such insights are required to define the roles of NLRP3 and IL-1β in host response to infection, and to establish a potential therapeutic application to this knowledge." (PMID 24312491, 2013). "WNV H8912 induced constitutive IL-10 production, upregulation of IFN-β and IL-1β expression, and a specific IgM response on day 10 post-infection." (PMID 23785537, 2013). "The pro-inflammatory cytokines IL-6 and IL-1β were significantly lower, after infection, in the lung compartment of panobacumab-treated animals as compared to untreated animals." (PMID 24023870, 2013). "Further, the increased virulence of IAV in a ferret infection model implicated NS1, a virus protein that targets RIG-I, decreasing both type I IFN and IL-1β secretion in epithelial cells." (PMID 23592984, 2013). "Once secreted, IL-1β mediates a variety of local and systemic responses to infection, such as induction of fever, promotion of T cell survival, B cell proliferation, and antibody production and mediates the transmigration of leukocytes." (PMID 23690844, 2013). "IL-1β is critical for host resistance to Mtb infection, demonstrated by the substantially reduced survival of IL-1β−/− or IL1R−/− mice after infection." (PMID 23762029, 2013). "Reduced pro-inflammatory cytokine concentrations by tulobuterol during RV14 infection in the present study are consistent with previous findings on the inhibitory effects of procaterol on the plasma levels of cytokines, including IL-1β, in rats." (PMID 24303127, 2013). "Nlrp3−/− and background C57BL/6 (WT) mice were infected by orogastric gavage, received IL-1β (0.5 μg/mouse; ip) on 0, 2, and 4 days post-infection (DPI), and assessed on 6 and 10 DPI." (PMID 24312491, 2013). "Activated NF-κB, also in chondrocytes, is known to be involved in the regulation of several genes, including by infection, adhesion, cell-cycle, apoptosis, survival and inflammatory processes, by activating IL-1β, TNF-α, IL-6, Cox-2 and MMPs." (PMID 24283517, 2013). "Upon arrival at the infection site, the activated neutrophils produce more cytokines including IL-1β which serve to mobilize additional neutrophils from the bone marrow." (PMID 24098366, 2013). "Our data indicated that although IL-1R1 pathway is essential for controlling acute infection by virulent M. tuberculosis, presence of either IL-1α or IL-1β allowed to survive acute M. tuberculosis infection." (PMID 25400917, 2013). "AdRas12V infection induced IL-1β expression more significantly than H2O2 treatment, whereas both treatments induced comparable mRNA and protein expression levels of NGF." (PMID 24198727, 2013). "MIP-2 is a C-X-C chemokine that attracts neutrophils to the site of infection and IL-1β is a pivotal mediator of inflammatory response." (PMID 24223208, 2013). "IL-1β has also been measured in nasal secretions after experimental infection of healthy volunteers with rhinovirus." (PMID 23723976, 2013). "Taken together, these data indicate that neutrophils were the predominant source of IL-1β for both the adoptive transfer experiments and the in vitro infection experiments." (PMID 23209417, 2012). "Caspase-1 activation has been reported to restrict bacterial infection either directly, by affecting bacterial growth, or indirectly, through IL-1β-mediated inhibition of infection." (PMID 22558425, 2012). "The levels of the chemokines KC, MIP-1α, MIP-2, and the pro-inflammatory cytokines IL-1β, IL-6 and TNFα further increased and peaked at day 2 of infection." (PMID 22347396, 2012). "Of note, a large proportion of these PLs comprised of monocyte-macrophage like cells and FV3 infections also elicited significantly increased expression of the macrophage pro-inflammatory genes (TNFα and IL-1β) in the PL populations." (PMID 22852041, 2012).
infection (continued). "The levels of myeloperoxidase (as neutrophil marker), TNFα, INFγ, GM-CSF, IL-1β and IL-6 transiently increased in lungs after infection, while levels of IL-10, IL-17A and IL-22 were indistinguishable from PBS controls." (PMID 22319619, 2012). "Interleukin-1 is necessary for the control of infection with M. tuberculosis, but the role of its two ligands, IL-1α and IL-1β, and its regulation in vivo are poorly understood." (PMID 23251798, 2012). "Prestimulation with TLR ligands is required for IL-1β production during infection of macrophages with C. muridarum." (PMID 22292031, 2012). "Using a mouse model of infection, we identified a central nervous system (CNS)-intrinsic requirement for the NLRP3 inflammasome and IL-1β signaling in limiting WNV associated disease within the CNS." (PMID 23209411, 2012). "After infection, both bacteria produced endotoxins and various cytokines released by activated monocytes/macrophages such as TNFα, IL1β, IFNγ etc. can promote HMGB1 translocation from nucleus to cytoplasmic organelles." (PMID 22947457, 2012). "We decided to focus on TLR2/4 since these TLRs are activated by RSV in immune cells like macrophages and previous studies have shown that TLR2/4 are involved in IL-1β secretion during infection with other pathogens." (PMID 22295065, 2012). "Interleukin-1β (IL-1β) is a critical cytokine that acts as a pyrogen to amplify the pro-inflammatory response during infection with various pathogens." (PMID 22295065, 2012). "Nevertheless, after 4 h and 8 h post infection the decrease in IL-1β secretion by esxA mutant infected cells is not only due to a lack in inflammasome activation but also to a decrease in pro-IL-1β production as determined by western blotting." (PMID 22911706, 2012). "Interleukin-1β (IL-1β) is a pro-inflammatory cytokine that regulates inflammatory responses to injury and infection." (PMID 22105559, 2012). "WT and NLRP3 KO BMDMs were infected with RSV and at 12 h and 24 h post-infection time periods medium supernatant was collected to assess IL-1β levels by ELISA." (PMID 22295065, 2012). "Using a mouse model of malaria infection, the same authors showed that the TLR9 response is particularly important in early infection to produce dendritic cell-derived pro-inflammatory cytokines although other mechanisms are required for IL-1β secretion." (PMID 23046548, 2012). "In mice which possess the Nlrp1bS gene, the inflamasome-mediated cell lysis promotes a pro-inflammatory response predominantly driven by IL-1β, which recruits immune cells to the site of LT exposure to resolve infection." (PMID 23162703, 2012). "In contrast, the majority of the IL-1β-expressing cells co localized with 7/4 at 4 hrs and especially at 24 hrs after infection." (PMID 23209417, 2012). "The early cytokine responses (TNFα, IL-6, IL-1β, IL-12) were measured on the first day of low-dose or high-dose infection." (PMID 23028333, 2012). "HIV-1∆Vpr-infected MDMs exhibited reduced infection over time and specifically a significant downregulation of IL-1β, IL-8 and TNF-α at the transcriptional and/or protein levels compared to HIV-1wt-infected cultures." (PMID 22727020, 2012). "Our results showed that upon infection wildtype BMMs produced IL-1β whereas IL-1β production in the Nlrp3 knockout macrophages was completely abolished." (PMID 22276187, 2012). "Individuals presenting with acute WNV infection displayed elevated levels of IL-1β in their plasma over the course of infection, suggesting a role for IL-1β in WNV immunity." (PMID 23209411, 2012). "To identify the NLR involved in IL-1β secretion, we infected bone marrow-derived wild type (wt) and knockout macrophages in NLRC4, NLRP3, ASC and Caspase-1 (all from C57BL/6 mice background) at MOI of 50 and quantified the IL-1β produced 24 h post-infection." (PMID 22848580, 2012).
infection (continued). "NLRP3 inflammasome serve as the platform for caspase-1 activation (and IL-1β release) during infection with both DNA (adenovirus, herpes virus, vaccinia virus) and RNA (influenza A virus, mouse Sendai virus, mouse encephalomyocarditis virus) viruses." (PMID 22295065, 2012). "Interleukine-1β (IL-1β) is the most studied pro-inflammatory cytokine, playing a central role in the generation of systemic and local responses to infection, injury, and immunological challenges." (PMID 23226286, 2012). "The serum levels of IL-1β in infected rats treated with water, however, were significantly higher at days 3 and 6 compared to day 28 post-infection suggesting that infection does alter circulating levels of this cytokine at least transiently." (PMID 23134838, 2012). "Overall, our results demonstrate that HIV-1 Vpr plays an important role in MDM infection as well as production of proinflammatory and neurotoxic cytokines IL-1β and IL-8 by infected/exposed MDMs." (PMID 22727020, 2012). "Next we demonstrated if these differences in IL-1β secretion can be detected already right after the 4h infection period and continued to persist during the 4 h and 8 h post infection timepoints." (PMID 22911706, 2012). "IL-1β is generated from the cleavage of pro-IL-1β by caspase-1 in inflammasomes after infections, and the downstream signaling cascade of the IL-1β-IL-1R interaction leads to the induction of various proinflammatory cytokines and the activation of lymphocytes." (PMID 22985464, 2012). "IL-1α, IL-1β, and the IL-1 receptor antagonistic molecule (IL-1 Ra) are expressed in the testis under normal homeostasis and they further increase upon infection/inflammation." (PMID 23251650, 2012). "IL-1β secretion was more evident when infected with more than 20 MOI indicating that it requires above a threshold level of infection." (PMID 22558229, 2012). "Infection with JEV for 3 h resulted in increased IL-1β and IL-18 mRNA levels in infected cells with respect to mock-infected condition." (PMID 22393394, 2012). "Cytokines in the serum, including IFN-γ and IL-1β were significantly increased at day 7, and raised levels of IL-1β and IL-12 in the spleen were present up to three weeks post-infection." (PMID 22738332, 2012). "The fact that 1 IL-1β and IL-8 are highly induced while C3 remains moderately expressed is consistent with the expected expression profile at the early stages of infection (3 days in our case)." (PMID 22429905, 2012). "We found that in vivo infection of OT induced IL-1β in the serum, suggesting that OT is able to do both priming and inflammasome activation during in vivo infection." (PMID 22723924, 2012). "During this in vitro infection, we observed increased production of IL-1β protein as the MOI increased from 1∶1 to 5∶1." (PMID 23209417, 2012). "Staining shows macrophages are present in the lamina propria at low dose infection of double mutant and are secreting only low amounts of IL-1β consistent with the low levels of colonization at 8 hours post inoculation." (PMID 22457618, 2012). "Infection with either isolate led to rapid increases in levels of IL-1β, IL-8 and IL-12 mRNA, with a later increase in IFN-γ mRNA levels as the infection was resolving." (PMID 23083136, 2012). "The actin polymerization inhibitor effectively blocked IL-1β processing and release by OT infection." (PMID 22723924, 2012). "Levels of IL-1β are increased in BALF from CF patients with infection and this increase has been temporally associated with a clinical response to treatment." (PMID 22649552, 2012). "Starting at day 1 post infection, control animals also had higher levels of several cytokines, including IL-1α, IL-1β, IL-6, IL-12p70, and IFN-γ in plasma, additionally IL-17 and TNF-α and chemokines (KC, MCP-1, MIP-1α) were elevated in lungs." (PMID 22448290, 2012). "At 12 h post-infection, the medium supernatant was collected to assess levels of secreted IL-1β by ELISA." (PMID 22295065, 2012).
infection (continued). "In vivo noninvasive whole animal imaging was then used to track the S. aureus bacterial burden while simultaneously monitoring IL-1β production or neutrophil recruitment in the same anesthetized mice over the 14 day course of infection." (PMID 23209417, 2012). "The induction of pro-IL-1β production is very similar right after the infection period as determined by western-blotting." (PMID 22911706, 2012). "Further study is needed to define the NLR inflammasome and ligand for IL-1β secretion upon OT infection, and to identify the mechanism which regulates pyroptosis." (PMID 22723924, 2012). "At 12 h and 24 h post-infection time-points, medium supernatant was collected to assess IL-1β levels by ELISA." (PMID 22295065, 2012). "Inflammasomes sense infection and cellular damage and are critical for triggering inflammation through IL-1β production." (PMID 23065753, 2012). "Although the co-localization of DsRed with the cellular markers does not provide information about how much IL-1β is made per cell, these data suggest that neutrophils represent the most abundant cell type that expresses IL-1β at the site of infection." (PMID 23209417, 2012). "Several of the mediators that are essential to the immune response and activation of lymphocytes can exacerbate infection and cause clinical symptoms when over produced in response to HHV-8 infection, including IFN-γ, IL-1β, IL-6, IL-8, TNF-α, and MCP-1." (PMID 23346088, 2012). "The precise mechanism is particularly relevant since many different cells, including keratinocytes, mast cells, Langerhans cells, dendritic cells and monocytes/macrophages, can produce IL-1β in various in vivo models of skin inflammation and infection." (PMID 23209417, 2012). "At 12 h and 24 h post-infection time-points, IL-1β levels in the medium supernatant were measured by ELISA assay." (PMID 22295065, 2012). "For example, we found peak induction of IL-1β mRNA in antigen-presenting cells occurs on day 3 post-infection in the neonatal ruminant RSV model." (PMID 22412984, 2012). "From a clinical point of view, these findings provide the basis for targeting IL-1β production by neutrophils to improve immunity against pyogenic infections, especially in patients with impaired neutrophilic responses." (PMID 23209417, 2012). "Unexpectedly, neutrophils but not monocytes/macrophages or other MHCII-expressing antigen presenting cells were the predominant source of IL-1β at the site of infection." (PMID 23209417, 2012). "In an in vitro macrophage infection, Y. pseudotuberculosis expressing YopP, the same strain used in a previous study triggered high levels of secreted IL-1β and cytotoxicity." (PMID 22563435, 2012). "In contrast, normal human bronchial epithelial (NHBE) primary cells (obtained from Lonza, Walkersville, MD) which are one of the primary targets of RSV during productive infection of human lungs produced IL-1β following RSV infection." (PMID 22295065, 2012). "Additional experiments are required to measure the release of IL1β following infection with S. aureus in order to confirm this link." (PMID 22792377, 2012). "The elevation of fluorescence intensity became apparent around 8 hours post infection, which corresponded to the initiation of IL-1β secretion in the culture supernatant." (PMID 22916014, 2012). "In this study, we systemically examined the role of IL-1 signaling in WNV infection to show that IL-1β signaling driven by the NLRP3 inflammasome acts to mediate protective immunity against infection." (PMID 23209411, 2012). "Compared to each monospecies infection, polybacterial biofilms impaired all wound healing parameters (p<0.01), and increased expression of IL-1β and TNF-α (p<0.05)." (PMID 22905182, 2012). "We observed that FV3 infection of tadpoles elicited relatively modest (10–100 times lower than adults) and delayed (3 days later than adult frogs) up-regulation of TNFα, IL-1β, IFNγ and MX1 genes in peritoneal leukocytes and in infected tissues of tadpoles." (PMID 22852041, 2012).
infection (continued). "Most interesting is the implied difference in regulatory T lymphocyte populations, evident from FOXP3 promoter site enrichment, and the potentially enhanced IL-1β expression as a result of greater up-regulation of CASP1 in the CA04 infection." (PMID 22937776, 2012). "Surprisingly, neutrophils themselves were determined to be the most abundant cell type that produced IL-1β during infection." (PMID 23209417, 2012). "Given this essential function of IL-1β, there has been intense interest in understanding how its production is triggered during an infection in vivo." (PMID 23209417, 2012). "The levels of IL-1β were high at day 4 after infection in db/db mice, which is also the peak of viremia." (PMID 22953001, 2012). "In that context, our current studies have elucidated both the first and second signals required for inflammasome mediated IL-1β release during infection with another clinically important human respiratory virus, RSV." (PMID 22295065, 2012). "The amount of IL-1β secretion from BMMs was increased in a multiplicity of infection (MOI)-dependent manner." (PMID 22916014, 2012). "Respiratory RNA viruses like RSV and influenza A virus induce secretion of IL-1β in the respiratory tract during infection of mouse and humans and its secretion is critical for “shaping” the anti-viral inflammatory response to clear virus from the airway." (PMID 22295065, 2012). "To test this we used LPS-treated primary murine peritoneal macrophages, as opposed to J774 macrophages, since there is a robust secretion of IL-1β from these cells in response to infection, whereas J774 cells, in our hands, fail to secrete IL-1β." (PMID 22563421, 2012). "Unexpectedly, the amount of IL-1β secretedfollowing infection with Yp-YopJKIM appeared to be lower inIkkβΔ BMDMs as compared toIkkβF/F macrophages, although the observeddifference was not statistically significant." (PMID 21533069, 2011). "The route of inoculation also impacted the kinetics of the response - serum IL-1β peaked on day 2 following IM inoculation but peaked on day 1 in BAL after IN infection; IL-12 peaked on day 1 following IM inoculation but on day 3 after IN infection." (PMID 21600020, 2011). "AIM2 is essential for the activation of caspase-1 and proteolytic processing of IL-1β and IL-18 in antigen presenting cells in response to infection with MCMV and VV." (PMID 21994762, 2011). "IL-1ra blocks the potent inflammatory IL-1β response which, if unregulated in infection, would result in host tissue damage." (PMID 21687657, 2011). "A great number of publications have documented the role of IL-18 and IL-1β during infections with a variety of pathogens." (PMID 22241982, 2011). "Infection of macrophages with Salmonella typhimurium, Shigella flexneri, Legionella pneumophila, and Pseudomonas aeruginosa all induce IL-1β secretion via activation of an NLRC4 inflammasome." (PMID 22019906, 2011). "Regarding the infection of microglial cells with M. tuberculosis and M. bovis, these microorganisms stimulated the production of IL-1A, IL-1B, TNF-α, G-CSF and GM-CSF; besides M. bovis stimulated the production also of IL-6." (PMID 22151930, 2011). "Regardless of the role of cytokines in response to LT challenge, it is clear that IL-1β is critical for resistance during infection with B. anthracis Sterne." (PMID 22241984, 2011). "Both viruses up regulated the IL-1β and IL-6, after infection in turkey cells, although the H5N9 stimulated a more robust response." (PMID 21939525, 2011). "Significantlylower levels of IL-1β (∼5-fold) were secreted from macrophages infectedwith Yp-YopJKIM in the presence of 30 mM KCl as compared to untreatedmacrophages at 8 hr post-infection." (PMID 21533069, 2011). "During the early phase of the infection the NLRC4 inflammasome also significantly contributes to IL-1β production." (PMID 22241982, 2011). "The infection of microglial cells with M. paratuberculosis stimulated the expression of IL-1A and IL-1B." (PMID 22151930, 2011).